VHL (von Hippel-Lindau tumor suppressor)
Diseases named in the same sentence as VHL in open-access papers (continued):
Sharing a sentence is not in itself a finding about the gene and the disease.
clear cell renal cell carcinoma (continued). "Nevertheless, knockout of VHL alone results in disorganized cilia and aberrant cell proliferation reminiscent of renal clear cell cancer in zebrafish, supporting a more direct involvement of VHL in ciliogenesis and cell-cycle control in this vertebrate model." (PMID 28361305, 2017). "However, it is important to note that in the case of VHL, four of the six likely pathogenic variants occurred in individuals from the TCGA cohort, which included 344 patients with a history of sporadic renal clear cell carcinoma who may be at an increased risk of harboring such germline variants." (PMID 29308445, 2017). "The VHL tumour suppressor gene is lost in approximately 70% of clear cell renal cell carcinoma (ccRCC)." (PMID 28643803, 2017). "A key feature of clear cell renal cell carcinoma (ccRCC) is the inactivation of the von Hippel-Lindau tumour suppressor protein (pVHL) that leads to the activation of hypoxia-inducible factor (HIF) pathway also in well-oxygenated conditions." (PMID 28680592, 2017). "Both the von Hippel-Lindau (VHL)/hypoxia-inducible factor (HIF) pathway and microRNA (miRNA) regulation are important mechanisms underlying the development and progression of clear cell renal cell carcinoma (ccRCC)." (PMID 26943772, 2016). "In clear cell renal cell carcinoma (CCRCC) VHL-defective RCC4 and RCC10 cells, binding of HIF-1α/2α to the reverse HRE (rHRE) on the HIF1A promoter, leads to H3K9 methylation, H3K4 de-methylation and HIF1A repression." (PMID 26647819, 2015). "Clear cell renal cell carcinoma is also characterized by VHL inactivation and more recent data indicate that VHL interacts with primary cilia in renal epithelial cells." (PMID 26579493, 2015). "In at least 60% of patients with sporadic clear-cell renal-cell carcinoma, the von Hippel–Lindau tumor-suppressor gene (VHL) is inactivated." (PMID 25373733, 2014). "Fuhrman grade and VHL status of the 30 clear cell renal cell carcinoma (ccRCC) specimens under study." (PMID 23785518, 2013). "For example, VHL dependent E-cadherin regulation by HIF-1α is carried out via this indirect form of regulation in clear cell renal carcinoma cells (CC-RCC)." (PMID 23469202, 2013). "Von Hippel-Lindau tumor suppressor (VHL) is lost in the majority of clear cell renal cell carcinomas (ccRCC)." (PMID 23922894, 2013). "Genetic and epigenetic changes in the von Hippel-Lindau (VHL) tumour suppressor gene are common in sporadic conventional (clear cell) renal cell carcinoma (ccRCC)." (PMID 22825683, 2012). "The most common type of kidney cancers, clear cell renal cell carcinoma (CCRCC), is associated with mutations of the VHL gene." (PMID 23178531, 2012). "The great majority of clear cell renal cancer involves inactivation of VHL, which acts as a gatekeeper tumour suppressor gene in renal epithelial cells." (PMID 21791076, 2011). "Familial mutations in VHL, a negative regulator of the HIF-α proteins, results in vascular tumors of the brain, spinal cord and retina, as well as appearance of renal clear-cell carcinomas." (PMID 21297970, 2011). "Clear cell renal cell carcinoma (CCRCC) is the commonest form of kidney cancer and the von Hippel-Lindau (VHL) tumour suppressor gene is mutated or inactivated in the vast majority of these tumours." (PMID 21791076, 2011). "In a large case-series of 470 sporadic clear cell renal cancer (ccRCC) cases, we examined von Hippel-Lindau (VHL) inactivation as a biomarker of tumor heterogeneity." (PMID 22022277, 2011). "Treatment with decitabine has been shown to lead to re-expression of VHL in clear cell renal carcinoma in vitro and in vivo through inhibition of DNA methylation in the VHL promoter region." (PMID 22414300, 2011). "The identification of the VHL gene and its critical role in renal malignancy has provided insight into the pathogenesis of sporadic clear cell renal carcinoma." (PMID 20109232, 2010).
clear cell renal cell carcinoma (continued). "The human VHL -/- clear-cell renal cancer cell line, 786-0, provides a model for investigating the effects of both HIFα isoforms, particularly HIF-2α, on tumor growth and metabolism in vivo, since it constitutively expresses only HIF-2α." (PMID 20652061, 2010). "The VHL/HIF axis in clear cell renal carcinoma always plays a key role." (PMID 40603319, 2025). "In contrast, positive feedback often leads to excessive cell proliferation, a prominent example of which is tumor formation, as exemplified by the VHL–histone lactylation–PDGFRβ positive feedback loop that contributes to accelerating the progression of clear cell renal cell carcinoma." (PMID 41413918, 2025). "There is no known association between VHL and breast cancer reported in the literature, and also no reported associations between VHL and urothelial cancer of the bladder apart from the established phenotype of clear cell renal cell carcinoma seen in VHL." (PMID 40051608, 2025). "Furthermore, to evaluate the influence of the VHL–HIF–E-cadherin pathway in clear cell renal cell carcinoma (ccRCC)." (PMID 41503066, 2025). "In addition to VHL, pathogenic or potentially pathogenic variants in the MET, FLCN, TSC1, TSC2, FH, and SDH genes also contribute to the development of clear-cell renal carcinoma." (PMID 39336594, 2024). "To further validate these findings, we examined the effect of USP43 loss in clear cell renal carcinoma cell (ccRCC) lines that have constitutive activation of both HIF-1 and HIF-2 (RCC4 cells, HIF-1α+, HIF-2α+ and VHL−), or only encode HIF-2α (786-0 cells, HIF-1α−, HIF-2α+ and VHL−)." (PMID 39009674, 2024). "This study explores the role of the von Hippel–Lindau (VHL) tumor suppressor gene and Lon protease in the development of clear cell renal carcinoma (ccRCC) through mechanisms involving inflammation and reactive oxygen species (ROS) accumulation in kidney cells." (PMID 39451551, 2024). "Autophagy activity and the expression of autophagy regulator LC3B are associated with the growth of clear cell renal cell carcinoma (ccRCC), which is characterized by the absence of von Hippel-Lindau tumor suppressor (VHL) in its early stages." (PMID 39633507, 2024). "Clear cell renal cell carcinoma, the most common form of RCC, is characterised by fatty acid and glycogen reprogramming that rewires this aberrant metabolism in ubiquitous ontology events of chromosome 3p deletion and VHL mutation or deletion." (PMID 36186457, 2022). "Clear cell renal cancers (KIRC) had significantly higher expression than normal tissue samples from the same project (p < 2.2 × 10−16), consistent with constitutive HIF activation resulting from loss of the VHL tumor suppressor gene." (PMID 36384128, 2022). "The absence of von Hippel-Lindau (VHL), a tumor suppressor gene, is a hallmark of clear cell renal carcinoma." (PMID 33912215, 2021). "We intentionally used clear cell renal cell carcinoma tissues, approximately 95% of which harbor deficiency in functional VHL, to analyze whether SPINK1 expression depends on the VHL–HIF-1 axis in human cancers." (PMID 34747365, 2021). "The clear cell renal cell cancer (ccRCC) cells frequently lack functional VHL." (PMID 34611473, 2021). "These inhibitors from the same substance class have been or are currently under investigation in phase II clinical trials targeting clear cell renal cell carcinoma (PT2385: NCT03108066), recurrent glioblastoma (PT2985: NCT03216499), and VHL-associated RCC (PT2977: NCT03401788)." (PMID 33466454, 2021).
clear cell renal cell carcinoma (continued). "pVHL functions largely as a tumor suppressor and germ line mutations in the VHL gene cause von Hippel–Lindau disease, a hereditary neoplastic disease associated with clear-cell renal-cell carcinomas (ccRCCs)." (PMID 32323143, 2020). "The most notable example would be the inactivation mutations of the von Hippel–Lindau tumour suppressor (VHL) gene which lead to the constitutive activation of HIF signalling and CAIX expression in clear cell renal cell cancers (ccRCCs) and the von Hippel–Lindau syndrome hemangioblastomas." (PMID 32570870, 2020). "That was the case for BRCA1, ERBB2 and ERBB3 loci that were found to be deregulated in triple-negative breast cancers or von Hippel-Lindau (VHL) tumour suppressor gene and PRCC that was linked to clear cell renal cell carcinoma and papillary renal cell carcinoma respectively." (PMID 31105870, 2019). "Clear-cell renal cell carcinomas (ccRCCs) are characterized by inactivation of the von Hippel-Lindau (VHL) gene and intracellular lipid accumulation by unknown pathomechanisms." (PMID 30173145, 2018). "Whereas VHL inactivation is a primary event in clear cell renal cell carcinoma (ccRCC), the precise mechanism(s) of how this interacts with the secondary mutations in tumor suppressor genes, including PBRM1, KDM5C/JARID1C, SETD2, and/or BAP1, remains unclear." (PMID 30355451, 2018). "Despite the general operation of the VHL-HIF system in the cellular response to hypoxia, VHL-associated cancer, which leads to constitutive up-regulation of HIF, is almost entirely confined to clear cell renal carcinoma, pheochromocytoma, and hemangioblastoma." (PMID 28715484, 2017). "The von Hippel-Lindau (VHL) tumor suppressor gene is often deleted or mutated in ccRCC (clear cell renal cell carcinoma) producing a non-functional protein." (PMID 29100286, 2017). "Although DNMTs have not been studied clinically as epigenetic agents that specifically target hypoxia, in vitro and in vivo inhibition of DNA methylation in the Von-Hippel Lindau tumor suppressor protein (VHL) promoter region by decitabine led to re-expression of VHL in clear cell renal carcinoma." (PMID 27384589, 2016). "Ectopic expression of VHL gene in renal clear cell carcinoma cell lines restored cilia formation, implying that pVHL might directly support ciliogenesis." (PMID 26579493, 2015). "Interestingly, we show that VHL-related renal clear cell carcinoma harbored disruption of VHL alone." (PMID 25298778, 2014). "VHL-regulated miR-204 is suppressed in VHL−/− renal clear cell carcinoma cells." (PMID 24025188, 2013). "Inactivation of the von Hippel-Lindau (VHL) gene occurs in patients with clear cell renal cell carcinoma in both the germline and somatic settings, whereas the underlying pathways that drive papillary RCC, particularly in the somatic setting, are less established." (PMID 21457556, 2011). "The Ser80Ile has been previously reported only in one VHL patient without clear cell renal carcinoma, but several other missense mutations at codon 80 have been described." (PMID 18416845, 2008). "When considering cases of renal clear cell cancers with a rate of VHL sequencing reaching 100%, the rate of mutations was not statistically different among patients who had been exposed to TCE and among those who had not, respectively 13% and 18%." (PMID 17997830, 2007). "Notably, the degradation of ATAD2 protein was observed in cell lines harboring mutant VHL, like clear cell renal cell carcinoma-derived cell lines, RCC4 and 786-O, upon hypoxic treatment, indicating that the regulation of ATAD2 protein was independent of the pVHL–HIF axis and its downstream genes." (PMID 38730681, 2024). "Pathogenic mutations in the von Hippel–Lindau (VHL) tumour suppressor impair its role as a master regulator of hypoxia-inducible factors (HIFs), leading to constitutive HIF activation and uncontrolled angiogenesis, increasing the risk of developing clear cell renal cell carcinoma (ccRCC)." (PMID 39336758, 2024).
clear cell renal cell carcinoma (continued). "Clear cell renal cell carcinoma (ccRCC) is one of the few adult cancers for which the VEGF-pathway targeted inhibitors consistently show substantial objective response rates, and it is characterized by loss of VHL gene product function (Shulman, Shi, & Zhang, 2021)." (PMID 39510293, 2024). "Furthermore, we resorted to publicly available HIF ChIP-seq data generated in a variety of renal tubule-derived cell lines including HKC-8, a proximal tubule-derived cell line, and RCC4 and 786-0 cells, which are VHL-defective clear cell renal cancer cell lines with proximal tubule origins." (PMID 37206967, 2023). "Moreover, in clear cell renal cell carcinoma, absence of VHL expression, due to VHL mutation and/or promoter hypermethylation, leading to HIF-1α constitutive activation, was associated with increased glycolytic metabolism." (PMID 30356832, 2018). "Furthermore, in clear cell renal cancer, von Hippel–Lindau (VHL) regulated MXRA5 expression." (PMID 27599751, 2017). "VHL inactivation in the pathogenesis of sporadic hemangioblastoma mirrors the VHL alterations seen in benign renal cysts, which may serve as precursors of clear cell renal cancer." (PMID 25589003, 2014). "A candidate gene for such an alteration is TCEB1, which encodes the required VHL binding partner elongin C and, in the recent genomic sequencing of clear cell renal carcinoma was found to be somatically mutated in the minority of cases that do not harbor VHL mutations." (PMID 25589003, 2014). "In clear cell renal cell carcinoma, ACLY expression is upregulated through HIF-2α/LPCAT1/FBXW7 and VHL/PPARγ axes, promoting lipid synthesis, tumor proliferation, and metastasis." (PMID 41958067, 2026). "The VHL-HIF pathway and lipid droplet accumulation are the main characteristics of clear cell renal cell carcinoma (ccRCC)." (PMID 38263248, 2024). "Histone lactylation triggered by inactive VHL could contribute to ccRCC progression through activating the transcription of PDGFRβ, and PDGFRβ can stimulate glycolysis, lactic acid production and the increase of histone lactylation in clear renal cell cancer cells." (PMID 39502530, 2024). "Moreover, the overexpression of Notch1 intracellular segment in VHL knockout mice revealed accumulation of intracellular fat, cytoplasmic dysplasia nests, and upregulated expression of Hey1 and Hey2 downstream of the Notch pathway, similar to human renal clear cell carcinoma." (PMID 35096263, 2022). "The most common kidney cancer, clear cell renal carcinoma, manifests upregulation of HIF owing to defective function of its E3 ubiquitin ligase, the von Hippel–Lindau tumor suppressor (VHL), and hyperactivation of mTOR1,2." (PMID 36097292, 2022). "Variation in VHL can cause familial erythrocytosis (ECYT2 [MIM: 263400]), von Hippel–Lindau syndrome (VHL [MIM: 193300]) and clear cell renal carcinoma (CCRC [MIM: 144700])." (PMID 33300982, 2021). "By considering the effect of the mutations upon the stability of the VHL protein and how they alter the affinity for its various binding partners, HIF-1α and Elongin B and C, we could accurately identify a patient's risk of developing clear cell renal carcinoma." (PMID 28408471, 2017). "In the past few years, therapies targeted at the von Hippel-Lindau (VHL) and hypoxia-inducible factor (HIF) pathways, such as sunitinib and sorafenib, have been developed to treat clear cell renal cell carcinoma (ccRCC)." (PMID 24783204, 2014). "The majority of clear cell renal cell carcinomas (ccRCCs) are triggered by the accumulation of HIF and the overexpression of downstream genes as a response to the inactivation of the von Hippel-Lindau (VHL) gene." (PMID 40837014, 2025). "While VHL inactivation is the primary driver of clear cell renal cell carcinoma, our study did not include in-depth research like genetic analysis of the tumor." (PMID 41584569, 2025).
clear cell renal cell carcinoma (continued). "Furthermore, SPAG4 upregulation in renal clear cell carcinoma (RCC), regulated by hypoxia via HIF-1 and VHL, has been shown to enhance tumor cell migration and invasion, while SPAG4 knockdown reduces RCC cell invasiveness in vitro." (PMID 39830981, 2024). "Examples include sporadic clear cell renal cell carcinomas with somatic-only biallelic inactivation of VHL or sporadic hemangioblastomas with or without the presence of LOH in the VHL gene, and not related to syndromic VHL disease." (PMID 36091175, 2022). "Von Hippel-Lindau (VHL) syndrome is a rare inherited cancer disease where the lack of VHL protein triggers the development of multisystemic tumors such us retinal hemangioblastomas (HBs), CNS-HBs, and clear cell renal cell carcinoma (ccRCC)." (PMID 35163250, 2022). "Von Hippel–Lindau (VHL), is a rare autosomal dominant inherited cancer in which the lack of VHL protein triggers the development of multisystemic tumors such us retinal hemangioblastomas (HB), CNS-HB, and clear cell renal cell carcinoma (ccRCC)." (PMID 32854260, 2020). "Here we explored whether there is connection between VHL and FLCN in clear cell renal carcinoma cell lines and tumors." (PMID 23922894, 2013). "Biallelic VHL inactivation is also common in sporadic (non-hereditary) clear cell renal carcinomas and hemangioblastomas." (PMID 21386990, 2011). "In the Oncomine database, FBXO11 mRNA levels were lower in normal tissues than in cancer tissues, including clear cell renal cell carcinoma (ccRCC), papillary renal cell carcinoma (pRCC), hereditary ccRCC, non-hereditary ccRCC, VHL mutant ccRCC and VHL wild-type ccRCC." (PMID 31159774, 2019). "Yuen and colleagues found that IGF1R protein levels are unaffected by hypoxia in clear cell renal carcinoma with or without VHL, but exogenously introduced VHL protein reduces both the promoter activity of IGF1R and the stability of IGF1R mRNA independent of oxygen concentration." (PMID 27460078, 2016). "However, the mechanism of DEC1 regulation in tumour cells must be VHL independent since, unlike conventional clear-cell renal cell carcinomas, breast cancers have an intact VHL gene." (PMID 15328513, 2004). "In clear cell renal cancer, HIF-α is constitutively stabilised irrespective of oxygen levels because of VHL inactivation." (PMID 36725335, 2023). "However, it is important to note that elevated plasma VEGF levels are also significantly increased in tumors without VHL alteration, suggesting the involvement of VHL-independent mechanisms in up-regulating VEGF in clear cell renal cell carcinoma (ccRCC)." (PMID 39272694, 2024).